MMP12 (matrix metallopeptidase 12)
Diseases named in the same sentence as MMP12 in open-access papers (continued):
Sharing a sentence is not in itself a finding about the gene and the disease.
infection (35 papers, 2008 to 2025). The state of being infected such as from the introduction of a foreign agent such as serum, vaccine, antigenic substance or organism. "In a previous study, we found that VDD mice were more susceptible to lung remodeling after a single infection with NTHi by expressing more MMP12." (PMID 35236342, 2022). "Furthermore, infection of matrix-metalloproteinase-12-deficient (Mmp12−/−) mice with the BeAn strain of TMEV resulted in an improved clinical course, reduced demyelination, as well as a reduced intralesional number of microglia/macrophages in the spinal cord." (PMID 30959793, 2019). "In the same time in vitro investigation demonstrated that infection with P. aeruginosa strain K induced NF-κB mediated MMP-12 expression in human airway epithelial H292 cells." (PMID 39011515, 2024). "Higher collagen deposition after infection in Cyb5r3 SPC–KO mice was accompanied by significantly higher transcript levels of Mmp12, Mmp13, Mmp14, and tissue inhibitor of metalloproteinases 1 (Timp1) but neither Timp2 nor Timp3." (PMID 36749633, 2023). "Western blot analysis of protein expression in IV-inoculated MLE-12 cells showed an upregulation of MMP-12 24h post infection." (PMID 37727782, 2023). "In summary, this cross sectional study has shown that smoking and bronchial colonisation/infection with Td are independently associated with elevated MMPs (aMMP8/MMP9 and MMP9/MMP12, respectively) in the bronchial fluid in a relatively large population." (PMID 26656474, 2015). "Bronchial colonisation/infection with Treponema denticola and smoking are independently associated with elevated MMPs (MMP9/MMP12 and MMP8/MMP9, respectively) in the bronchial fluid." (PMID 26656474, 2015). "Mmp12−/− mice were shown to have impaired bacterial clearance and increased mortality upon infection with gram-positive bacteria." (PMID 21857913, 2011). "Of note, the disruption in PNN formation during infection was associated with increased expression of MMP-12 and -19 but not MMP-9 or ADAMTS-4 or -5, which have been previously shown to be increased in some disorders where established PNNs are disrupted." (PMID 37496706, 2023). "Besides, MMP9 and MMP12 were highly expressed in lung lesions in CSE-exposed mice with BCG-infection." (PMID 32973788, 2020). "In addition, TMEV infection of Mmp12−/− mice leads to a reduced degree of demyelination, supporting the assumption that MMP12 substantially contributes to demyelination." (PMID 30959793, 2019). "Collectively, these findings suggest that, in gingiva, the upregulation of MMP12 may be a molecular hallmark of natural aging, while the upregulations of MMP3, MMM9, and IL1B may indicate externally (e.g., infection)-induced aging." (PMID 27391467, 2016). "However, in CS-exposed mice, both IAV and RSV infections synergistically enhanced MMP-12 mRNA expression with IAV infection more than RSV." (PMID 27363862, 2016). "The top upregulated genes in KSHV lytic and mixed infection spots are predicted to encode proteins that regulate angiogenesis including ADAMTS9, KDR and PGF, endothelial cell development including KDR and STC1, and cell-substrate adhesion, SPRY4, ITGA1, ADAMTS9, KDR, MMP12." (PMID 39386738, 2024). "A significant increase in the expression of MMP1, MMP3, MMP9, MMP12, MMP13, and MMP14, was noted in Mtb-AG infected, compared with Mtb-SC-infected rabbit lungs, at both 1 and 4 weeks post infection." (PMID 34732811, 2021). "Three days post infection, CS + IAV mice had increased mRNA expression of pro-inflammatory chemokines (CCL-2, CXCL-2), cytokines (GM-CSF, TNF-α, IL-1β, IL-6) and proteases (MMP-12) compared to sham + IAV + diluent mice." (PMID 26877172, 2016). "The differential gene expression observed at day 15 post-infection demonstrated a consistent pattern of gene up regulation of PHGDH and PSAT1 and down regulation of APOC1, FADS2, FXYD2, KIAA0125, and MMP12 over a period of time in HIV-1 infected PBMC." (PMID 26821323, 2016).
infection (continued). "Seven days post infection, CS + IAV mice had increased mRNA expression of pro-inflammatory chemokines (CCL-2, CXCL-2), cytokines (GM-CSF, TNF-α, IL-1β, IL-6) and proteases (MMP-12) compared to sham + IAV + diluent mice." (PMID 26877172, 2016). "Furthermore, in different strains, gene expressions of MMP12 and PPARD under the infection of C. albicans SC5314 are higher than C. albicans WO-1." (PMID 30769958, 2019). "Three days post infection, sham + IAV + vehicle mice had increased mRNA expression of pro-inflammatory chemokines (CCL-2, CXCL-2, CXCL-10), cytokines (GM-CSF, TNF-α, IL-1β, IL-6) and proteases (MMP-12) compared to sham + diluent + vehicle mice." (PMID 26877172, 2016). "Seven days post infection, CS + IAV mice had increased mRNA expression of pro-inflammatory chemokines (CCL-2, CXCL-2, CXCL-9, CXCL-10), cytokines (GM-CSF, TNF-α, IL-1β, IL-6) and proteases (MMP-12) compared to sham + IAV + diluent mice or CS + diluent mice." (PMID 26877172, 2016). "Although IAV was used at a lower titer, IAV, but not RSV infection increased MMP-12 mRNA levels in FA-exposed mice." (PMID 27363862, 2016). "In search of the culprits that are responsible for airway disorders in the absence of T cells and IFN-γ, we found that MMP-12 levels were substantially increased in nude mice at days 3, 5, 7 and 9 post-infection." (PMID 25652021, 2015). "Infection also induced the expression of co-stimulatory molecules such CD40, CD83, CD86, adhesion molecules (CD38, Itga5, and ICAM1), and tissue invasion molecules such as MMP12 and MMP14." (PMID 22928052, 2012). "However, in response to infection, male mice exhibited higher expression levels of CDKN1B, and CTNNB1 (KO, 1A3), TCF4 (1A0, 6A2), TAP1, and TAP2, (1A0), CDKN1A, (1A3, 6A2), MARCO, and MMP12 (1A3), CCND1, CDK2, IRF and MYC (6A2) compared to females." (PMID 32670284, 2020). "However, infection or inflammation may amplify the action of LMW-HAs via interactions with hyaladherins, leading to an increase in the secretion of cytokines (TNF-α, IFN-β, IL-6), chemokines (IL-8), ROS, or enzymes (NE, MMP-9, MMP-10, MMP-12)." (PMID 35625586, 2022). "In chondrocytes overexpressing ERRγ via infection with Ad-Esrrg, MMP-3 and MMP-13 mRNA levels were dramatically elevated without affecting MMP-12 and ADAMTS5." (PMID 33261216, 2020).
cardiovascular disease (11 papers, 2011 to 2025). "While circulating levels of MMP12 have been linked to increased risk of cardiovascular disease, genetically increased MMP12 has been linked to reduced cardiovascular disease risk in the current report as well as others." (PMID 33210602, 2020). "These associations between MMP9 or MMP12 and cardiovascular disease indicate that more basic research and clinical studies are needed to confirm the diagnostic significance and therapeutic potential of MMP9 and MMP12." (PMID 35842645, 2022). "Consequently MMP12 cleavage may underlie the increased circulating levels of galectin-3 observed in patients with cardiovascular diseases, particularly given that commercially available ELISAs for galectin-3 do not discriminate between full-length and cleaved forms of galectin-3." (PMID 32295421, 2020).
inflammation (8 papers, 2013 to 2025). Aberrant reaction of the microcirculation characterized by movement of fluid and leukocytes from the blood into extravascular tissues. "Our study demonstrates that the enzyme MMP-12 is upregulated in allergen-challenged mice and in IL-13-overexpressing mice exhibiting cytokine-driven airway inflammation." (PMID 40940719, 2025). "Inhibition of MMP-12 or ERK signaling pathway in vivo both diminished LPS-driven lung inflammation and AHR." (PMID 32693803, 2020). "The ELA group exhibited increases in alveolar neutrophil infiltration, the numbers of TNF-α, MAC-2, MMP-9, MMP-12, TIMP-1, eNOS, and iNOS-positive cells and the volume fraction of the 8-iso-PGF2 α, suggesting the presence of lung inflammation, remodeling, and oxidative stress processes." (PMID 27528793, 2016).
Neurologic Disease (5 papers, 2018 to 2025). "Actually, MMP-12 has been proposed as a promising therapeutic target for neurological diseases, including ICH." (PMID 39069622, 2024). "Also, data on the varicella zoster virus (VZV) neurologic disease in humans suggest involvement of multiple MMPs, with an increased concentration of MMP2 and to a lesser degree of MMP3 and MMP9 both in serum and CSF, as well as of MMP8 and MMP12 in CSF only." (PMID 40003967, 2025).
bacterial infections (3 papers, 2013 to 2021). "Nos2 expression helps to control bacterial infections such as S. aureus and MMP12 plays a role in early killing of S. aureus in the phagolysosome of MΦ." (PMID 27010826, 2016).
vasculopathy (3 papers, 2014 to 2023). "Moreover, previously published studies have shown that matrix metalloproteinase (MMP)-12 overexpression cleaves uPAR, impairs angiogenic endothelial cell turnover, and inhibits uPA-mediated angiogenesis thus causing vasculopathy." (PMID 37958542, 2023). "Here we demonstrate that Ang II also induces prominent vascular injury that recapitulates several aspects of SSc vasculopathy, including elevated levels of MMP-12 in the skin and in the hearts of Ang II-treated mice." (PMID 25302498, 2014).
respiratory diseases (2 papers, 2017 to 2019). "Less is known of the role of MMPs in other respiratory disease such as asthma, with MMP-9 and MMP-12 being reported to increase in the airway smooth muscle of fatal asthmatics and mouse knockout studies indicating that several MMPs may be involved in fibrosis." (PMID 28596972, 2017).
cardiac disease (1 paper, 2024). "Thus, the decreased expression of MMP12 would enhance the cardiac disease preventing inflammation resolution." (PMID 39000601, 2024).
connective tissue disease (1 paper, 2025). "Concerning early connective tissue disease (CTD)-ILD+ diagnosis, increased MMP-7, MMP-9, MMP-10, and MMP-12 levels were found in RA-ILD+ and SSc-ILD+ patients in relation to RA-ILD- and SSc-ILD- patients, respectively." (PMID 39979794, 2025).
immune dysfunction (1 paper, 2024). "Taken together, our results demonstrated a limited contribution of MMP-12 to the immune dysfunction in LAL-D." (PMID 39456786, 2024). "However, pathologies observed in Mmp12-overexpressing mice, such as immune dysfunctions, may have been alleviated in Lal/Mmp12 DKO mice." (PMID 39456786, 2024).
renal disease (1 paper, 2016). "The results indicate that MMP-12 modulates glomerular fibrogenesis and inflammation in renal disease induced by HFD, and suggest that drugs that target MMP-12 can be effective in preventing CKD." (PMID 26822129, 2016).
retinopathy (1 paper, 2012). "The present study aims to explore the enzyme’s contributions to retinal angiogenesis in oxygen-induced retinopathy (OIR) using MMP-12 knockout (KO) mice." (PMID 23285156, 2012).
MMP12 also shares sentences with these, for which no sentence is quoted: chronic periodontitis (3 papers); endothelial dysfunction (3); idiopathic pulmonary fibrosis (3); adenocarcinoma (2); arteriosclerosis (2); Breast tumor (2); oral squamous cell carcinoma (2); pneumonia (2); primary open-angle glaucoma (2); psoriatic arthritis (2); tuberculosis (2); acute coronary syndrome (1); acute lung injury (1); acute myeloid leukemia (1); acute respiratory distress syndrome (1); Adamantinomatous Craniopharyngioma (1); age-related macular degeneration (1); allergic rhinitis (1); ameloblastoma (1); anemia (1); aortic atherosclerosis (1); aortic insufficiency (1); aortic valve disease (1); ascariasis (1); atrial fibrillation (1); brain tumor (1); chronic asthma (1); chronic gastritis (1); chronic hepatitis C infection (1); chronic rhinosinusitis with nasal polyps (1).
A further 50 diseases each share a sentence with MMP12 in 1 paper.